STAT3 (signal transducer and activator of transcription 3)
Diseases named in the same sentence as STAT3 in open-access papers (continued):
Sharing a sentence is not in itself a finding about the gene and the disease.
tumor (continued). "Our study further elucidates a functional mechanism where EFNA1 cis-interacts with its receptor EphA2, leading to EphA2 degradation and subsequent activation of the Src/AKT/STAT3 pathway, thereby promoting tumor progression in CC." (PMID 39964764, 2025). "IL-6 secretion activates the STAT3 signaling pathway in tumor cells, promoting survival, proliferation, and resistance to Deoxyribonucleic Acid (DNA)-damaging agents, such as cisplatin." (PMID 40940809, 2025). "Collectively, our results indicate that M2‐TAM infiltration and upregulated STAT3/NF‐κB pathways drive tumor proliferation, angiogenesis, EMT, and immunosuppression, leading to poor clinical outcomes." (PMID 41263059, 2025). "While this study demonstrated the efficacy of STAT3 inhibition via TTI-101 in reducing tumor burden and in reprogramming inflammation in KM-LUAD, several limitations should be addressed." (PMID 40356899, 2025). "To further confirm that the STAT3 pathway mediates the anti‐tumor activity of IDET, we overexpressed STAT3 in TNBC cells." (PMID 40918170, 2025). "Collectively, these results suggest that tumor cell–derived lactate regulated the ENSA-K63la/SRC-pS12/STAT3-pY705 axis in TAMs." (PMID 39883522, 2025). "IL-6 activates the JAK/STAT3 signaling in tumor cells and tumor-infiltrating immune cells, participating in the construction of an adverse TIME, potentially facilitating AST." (PMID 40568576, 2025). "STAT3 protein expression was detected in 56% of tumor samples and 69% of the immune microenvironment." (PMID 40426911, 2025). "Its activity is modulated by multiple oncogenic pathways, including Wnt/β-catenin, PI3K/AKT, STAT3, and NF-κB, as well as through chromatin remodeling and tumor microenvironmental cues." (PMID 40722714, 2025). "Collectively, our study unveils the critical role of SEs in promoting tumor progression through the FOSL2-EFNA1-EphA2-Src/AKT/STAT3 axis, providing new prognostic and therapeutic avenues for CC patients." (PMID 39964764, 2025). "Since PTPRO can suppress tumour progression and metastasis by targeting STAT3 and JAK217, we focused our research on the JAK2/YAP pathway." (PMID 40016288, 2025). "Activation of STAT3 and NF-κB can directly promote tumor cell survival, proliferation, metastasis, EMT, angiogenesis, and immune suppression." (PMID 40863244, 2025). "Comparative analysis of the combined GTEx and TCGA datasets demonstrated significantly lower STAT3 expression in tumor tissues compared to normal breast specimens (p < 0.001)." (PMID 40636126, 2025). "Double KD of HRH1 and STAT3 in HSC-3M cells exhibited the strongest inhibitory effect on tumor growth compared to either HRH1-KD or STAT3-KD alone." (PMID 40113769, 2025). "This interaction prevents activated STAT3 from accumulating in tumor cell nuclei, leading to a significant reduction in tumor growth." (PMID 40166646, 2025). "STAT3 has been reported to be related to tumour cell growth, immunosuppression, and chronic inflammation." (PMID 40118773, 2025). "The PI3K/AKT/mTOR and JAK/STAT3 signaling cascades are commonly aberrant in skin malignancies, facilitating tumor persistence by exerting anti-apoptotic effects and driving proliferative expansion." (PMID 40399946, 2025). "proved that quercetin exhibits anti‐tumor effects in HCC LM3 cells by blocking the JAK2/STAT3 signaling pathway." (PMID 40347062, 2025). "Calcitonin gene-related peptide (CGRP) has also been shown to markedly promote tumor growth through extracellular signal-regulated kinases (ERKs)/signal transducer and activator of transcription 3 (STAT3) signaling pathways." (PMID 41163091, 2025). "STAT3 pRNA induces the apoptosis of tumor cells and facilitates the release of specific tumor antigens." (PMID 40006583, 2025). "Postdegradation, they can significantly inhibit STAT3 target gene expression and tumor cell proliferation, possessing broad‐spectrum immunoregulatory capabilities." (PMID 41049269, 2025).
tumor (continued). "CAF-secreted IL-6 can activate STAT3 signaling in tumor and immune cells, which in turn upregulates PD-L1 expression and impairs CD8+ T cell–mediated cytotoxicity." (PMID 41583435, 2025). "AST suppresses tumor growth and triggers cell death by lowering Akt activity, which in turn inhibits NF-κB, STAT3, and Wnt pathways via decreased p-Akt/Akt levels." (PMID 40565712, 2025). "The anti-histamine drug ketotifen effectively induces apoptosis of NEPC tumor cells by targeting the interleukin-6 (IL-6)/signal transducer and activator of transcription 3 (STAT3) pathway, which reduces the survival rate of NEPC." (PMID 40746825, 2025). "The STAT3 signaling pathway, crucial for tumor growth and survival, was significantly inhibited by faberidilactone A, as evidenced by reduced STAT3 phosphorylation and downregulation of downstream targets such as cyclin D1 and Mcl-1." (PMID 40076318, 2025). "PKM2’s SUMOylation promotes interaction with ARRDC1 and secretion via exosomes into the tumor microenvironment, activating STAT3 phosphorylation in monocytes and inducing their metabolic reprogramming and differentiation into macrophages." (PMID 40842995, 2025). "Cyclooxygenase 2 (COX2), a rate-limiting enzyme responsible for PGE2 biosynthesis, is not expressed in most normal tissue but is rapidly induced in response to several tumor promotors and cytokines mainly through NF-κB and STAT3 signalings." (PMID 39826687, 2025). "For instance, exosomal miR-1246 and miR-92a-3p derived from tumor cells have been shown to activate STAT3 and ERK signaling pathways in TAMs, promoting their polarization toward an immunosuppressive M2 phenotype." (PMID 40873588, 2025). "The recent evidence from both preclinical and clinical studies has established that STAT3 plays a critical role in TNBC, and that STAT3 inhibitors have shown efficacy in inhibiting TNBC tumor growth and metastasis." (PMID 41516003, 2025). "Prior research has indicated that nuclear CD44/acetylated-STAT3 complexes enhance the outgrowth of cells into structures resembling CSCs, promoting tumor formation." (PMID 40083697, 2025). "TAM-derived cytokines such as IL-6 and TNF-α activate signaling pathways like STAT3 and NF-κB in tumor cells, inducing EMT and increasing metastatic potential." (PMID 41280929, 2025). "Given the roles of AKT and STAT3 in tumor proliferation, we assessed the expression levels of AKT, STAT3 and their phosphorylated activation forms using Western blot analysis." (PMID 40563476, 2025). "EZH2 also plays a role in the activation of STAT3 signaling, which is involved in tumor cell migration, invasion, and angiogenesis." (PMID 39858107, 2025). "To investigate the in vivo effects of CXCL14 knockdown or blockade of the CXCL14/CCR7/STAT3 axis within the tumor microenvironment (TME), we coinjected CAFs and T24 cells, each with different shRNAs, subcutaneously into nude mice." (PMID 40898244, 2025). "Sustained activation of STAT3 can promote tumor cell growth and survival and help tumors escape immune surveillance." (PMID 40944417, 2025). "In the development of malignant tumors, the JAK2/STAT3 signaling pathway primarily participates in the regulation of biological functions such as tumor cell growth, proliferation, migration, invasion, and apoptosis." (PMID 40936898, 2025). "Inhibiting the nucleo-cytoplasmic translocation of HMGB1, particularly through ICM treatment, reduces STAT3 activation and PD-L1 expression, leading to decreased tumor growth in vivo." (PMID 40389855, 2025). "In contrast to the tumor suppressor STAT1, which is a marker for favorable prognosis in different tumor types, the homologous STAT3 fulfills cell-autonomous functions in many cancer cells through maintaining stemcellness and promoting proliferation." (PMID 40287766, 2025). "Recent studies indicate that EZH2, through its interaction with pathways such as STAT3, contributes to immune evasion by upregulating PD-L1 expression, which facilitates tumor progression." (PMID 40038276, 2025).
tumor (continued). "TNBC-derived EVs also induce macrophage polarization towards an M2 phenotype, creating a tumor-supportive environment via IL-6/STAT3 and NF-κB pathways." (PMID 40103824, 2025). "ER stress-inducible TMTC3 markedly increased tumor angiogenesis through the activation of the Rho GTPase/STAT3 pathway in ESCC." (PMID 40821803, 2025). "The literature describes an interaction between this protein and STAT3 in the regulation of tumor metabolic processes." (PMID 40141386, 2025). "As an m5C reader, ALYREF stabilizes oncogenic transcripts—such as EGFP—thereby promoting downstream signaling pathways like STAT3, which are known to drive tumor progression." (PMID 41012587, 2025). "A latest investigation into its molecular mechanism found that the hypoxia-selective BE-43547A2 exerts its anti-tumor effects through a sophisticated regulation of the HIF1α-eEF1A1-FoxO1-JAK/STAT3 signaling axis." (PMID 40806463, 2025). "Compelling evidence suggests that suppressing expression or blocking activation of STAT3 significantly inhibits tumor progression, and most normal adult tissues are spared from the effects of STAT3 deletion." (PMID 40118821, 2025). "The loss of PBRM1 was noted to lead to increased HIF transcription, STAT3, and mTOR signaling, thereby favoring tumor growth." (PMID 40725144, 2025). "Since these cytokines are transcriptionally regulated by NF-κB and STAT3, it is likely that CTRP6-driven ERK activation intersects with these pathways to sustain tumor-associated inflammation." (PMID 41228203, 2025). "In cell models of leukemia, SD-36 completely abolishes STAT3, suppressing the expression of its targets and arresting tumor cell growth." (PMID 40650173, 2025). "In colorectal cancer, heightened STAT3 expression correlates with tumor invasion, lymph node metastasis, and tumor progression." (PMID 40166646, 2025). "Genetic ablation or pharmacologic inhibition of Stat3 in myeloid cells leads to the M1 phenotype and increased antitumor immune responses in several mouse tumor models." (PMID 40801626, 2025). "IL-6, in turn, can facilitate tumor progression through various mechanisms, including the promotion of inflammatory responses, the upregulation of key proteins involved in tumor proliferation and migration, and the activation of the STAT3 pathway." (PMID 41403696, 2025). "Chronic inflammation stimulates tumor growth and development through key cytokines, such as nuclear factor kappa-B (NF-κB) and signal transducer and activator of transcription 3 (STAT3)." (PMID 40297806, 2025). "In mCRPC, PMN-MDSCs contribute to resistance by secreting interleukin-23 (IL-23), which activates STAT3–RORγ signaling in tumor epithelial cells." (PMID 41228234, 2025). "The downregulation of SOCS3 activates the JAK2/STAT3 signaling pathway and promotes tumor metastasis." (PMID 40275278, 2025). "The STAT3 signalling pathway, as a collection of multiple oncogenic signalling pathways, plays powerful and diverse roles in a wide range of diseases and tumours." (PMID 40415238, 2025). "To address this gap, we aimed to develop a non-invasive radiomics approach using DCE-MRI to predict STAT3 expression and assess tumor immune status." (PMID 40636126, 2025). "For example, enhanced STAT3 transcriptional signal can increase glycolysis and promote tumor progression." (PMID 39905019, 2025). "Mechanistically, downregulation of SLC9A2 activates the STAT3 pathway in tumor cells, promoting their migration and invasion." (PMID 40474298, 2025). "To further interrogate the role of ITGB3 as a critical downstream effector of STAT3-mediated human tumor initiation in vivo, we performed a limiting dilution assay to compare the ability of FG STAT3WT vs. FG STAT3KO cells to establish tumors in nude mice." (PMID 40701148, 2025). "STAT3 is known to be activated in many cancers and facilitates cross-regulation of tumor and immune cells." (PMID 41463176, 2025).
tumor (continued). "Upregulation of miR-125a and let-7e, which target IL-6, the IL-6 receptor, and STAT3, exerts anti-VM effects and sensitizes tumor cells to chemotherapy." (PMID 41400702, 2025). "COX-2 has been shown to modulate tumor cell proliferation, migration, metabolism, and angiogenesis through control of various genes associated with key pathways, including JAK/STAT3, WNT/β-catenin/TCF, and PI3K/AKT." (PMID 41009473, 2025). "EGFR activation has been shown to interact with inflammatory pathways such as NF-κB and IL-6/STAT3, leading to enhanced tumor proliferation, angiogenesis, and an immunosuppressive microenvironment." (PMID 41268168, 2025). "These drugs target the STAT3 signaling pathway, which is involved in tumor progression and immune evasion." (PMID 40735045, 2025). "Tumor cells upregulate activated STAT3 to enhance cell cycle progression, angiogenesis, and prevent apoptosis." (PMID 40529368, 2025). "The NF-κB pathway, for example, is particularly involved in regulating genes that support inflammation, while STAT3 is crucial for the survival and expansion of tumor cells, particularly under inflammatory conditions." (PMID 39941451, 2025). "Among the other 24 cancers, 12 showed statistically significant differences in STAT3 expression between the tumor and normal tissues." (PMID 40265014, 2025). "STAT3 ablation at this stage significantly reduces tumor establishment and increases HFSC apoptosis." (PMID 40399946, 2025). "PD-L1 silencing resulted in reduced tumor growth, demonstrating the role of STAT3 in promoting proliferation and growth through modulation of PD-L1 gene expression." (PMID 40507264, 2025). "By inhibiting IL6, it is possible to reduce the phosphorylation of STAT3, thereby decreasing the proliferation and anti-apoptotic capabilities of tumor." (PMID 40535567, 2025). "Conditional deletion of Stat3 in a neutrophil-specific manner (Ly6GcreStat3fl/fl mice) significantly impaired tumor growth and metastasis in mice." (PMID 40885734, 2025). "STAT3 is an important transcription factor in tumor progression, and its activation is pivotal in regulating the expression of EMT-related genes/proteins, such as Twist, Vimentin, Snail, MMPs, and ZEB1, essential proteins in metastasis." (PMID 39412616, 2025). "While STAT3 is known to play an important role in DC maturation, DC-specific knockouts of STAT3 in mice result in DCs that are fewer in number but greater in anti-tumor function and Th1 priming ability via IL-12 secretion." (PMID 40356899, 2025). "BFT also influences immune cells by activating the TLRs signaling pathway, which upregulates IL-6 and TNF-α, further leading to the activation of STAT3 and NF-κB, thereby inhibiting anti-tumor immunity and promoting tumorigenesis." (PMID 40297806, 2025). "While our model does not exclusively target perineural GBM, the findings are relevant due to STAT3’s general role in tumor progression." (PMID 40427146, 2025). "Consistent with these recent findings, our study highlights a potential role for STAT3 as a tumor suppressor in NB." (PMID 39843641, 2025). "This is because mTOR can activate the STAT3 pathway and together, the mTOR/STAT3 pathway promotes the development of tumours." (PMID 40407951, 2025). "In ESCC, aberrant activation of the JAK/STAT pathway—particularly phospho-STAT3 overexpression—has been frequently observed and is correlated with advanced tumor stage, lymph node migration, and poor prognosis." (PMID 41476794, 2025). "In this study, we demonstrated that inhibiting STAT3 with TTI-101 is an efficacious means of targeting a myriad of pro-tumor STAT3 functions across the tumor and immune compartments." (PMID 40356899, 2025). "Once a tumor is established in the human body, the inflammatory environment created by tumor cells can activate the NF-κB and STAT3 signaling pathways." (PMID 40487290, 2025).
tumor (continued). "In cancer, STAT3 is often constitutively activated, leading to the transcription of genes that promote tumor growth and survival, angiogenesis, and immune evasion." (PMID 40170567, 2025). "Knockdown of HDAC7 has been shown to reprogram STAT3 signaling, thereby suppressing angiogenesis and tumor growth." (PMID 40450300, 2025). "The combination treatment inhibited the EGFR/JAK/STAT3 signaling pathway and reduced PD-L1 expression, concurrent with increased immune-mediated tumor cell death through the perforin/granzyme B pathway." (PMID 40347254, 2025). "Evidence also highlights PRLR’s role in various cancers, acting through pathways like JAK2/STAT3 to regulate tumor cell proliferation, survival, invasion, and immune evasion." (PMID 40978029, 2025). "To further elucidate the molecular consequences of JAK2/STAT3 inhibition, we assessed the expression of downstream effectors involved in tumor proliferation, inflammation, apoptosis, and metastasis." (PMID 41200213, 2025). "TSM-1 has demonstrated robust anti-tumor effects in STAT3-dependent HNSCC models, particularly in patient-derived xenografts (PDXs) and patient-derived organoids (PDOs)." (PMID 40426875, 2025). "Systemic delivery of the unformulated ASO, AZD9150, decreased STAT3 expression among preclinical models (human primary patient-derived tumor explant models, included NSCLC, colorectal cancer, and lymphoma)." (PMID 40428391, 2025). "The STAT3 inhibitor WP1066 disrupts this loop and STAT3 signaling in ECs, thereby suppressing tumor angiogenesis." (PMID 41514658, 2025). "IL-6 secreted by CAFs activates the JAK/STAT3 pathway in tumor cells, promoting proliferation via cyclin D1 upregulation." (PMID 41311372, 2025). "NF-κB and STAT-3 work together to control a common set of cytokine and chemokine coding genes that are involved in tumor development." (PMID 40786506, 2025). "Overexpression of miR-10a-5p was found to downregulate STAT3 phosphorylation, TFR1, and CD24 expression, indicating that miR-10a-5p influences tumor immune escape via the TFR1/STAT3 axis." (PMID 41551164, 2025). "Our findings are consistent with those of other studies.For example, in tumor-associated B cells, STAT3 promotes CTLA4 expression in a JAK-dependent mechanism, while in Treg cells, STAT3 promotes CTLA4 expression via IL-10." (PMID 40092547, 2025). "In our study, we initially found that inhibiting the phosphorylation of STAT3 is essential for the anti‐tumor effects of IDET against TNBC." (PMID 40918170, 2025). "This protein is found to be a tumor suppressor in GB, by negatively regulating STAT3 activity that upon activation promotes self‐renewal and prevents apoptosis." (PMID 39417309, 2025). "This pathway reduces ERK activity, a tumor growth inhibitor, while enhancing STAT3 phosphorylation, which promotes tumor proliferation." (PMID 40136375, 2025). "Activation of STAT1 is generally associated with antitumor immune responses that promote antigen presentation and cytotoxic T cell recruitment, while activation of STAT3 often promotes tumor cell survival, angiogenesis and immunosuppression." (PMID 40760734, 2025). "This dual iron overload elevates mitochondrial reactive oxygen species, activates STAT3 signaling, and enhances tumor cell proliferation." (PMID 41041538, 2025). "The STAT3 pathway in MDSCs has been shown to promote both Immune Evasion and tumor proliferation through a dual mechanism involving immunosuppression and metabolic deprivation." (PMID 41333481, 2025). "Expression of STAT3 in tumor cells is known to drive an immunosuppressive microenvironment through secreted mediators such as IL-6 and IL-1031." (PMID 41509421, 2025). "In summary, the interplay between hypoxia (governed by HIF-1α) and chronic inflammation (driven by NF-κB and STAT3) creates a self-reinforcing network that fosters tumor malignancy." (PMID 41302515, 2025).